ENSG00000286131 (novel protein)
Synonyms: LOC128092250
Gene: Protein-coding gene on chromosome 8 (32,647,202 to 32,647,390, forward strand). Ensembl gene ENSG00000286131.
Genetic constraint (gnomAD): Loss-of-function variants: 1 observed, 3.06 expected, observed/expected ratio (o/e) 0.33, 90% interval 0.11 to 1.45. That is too few expected variants to judge how well the gene tolerates losing a copy. Missense variants: 48 observed, 77.27 expected, observed/expected ratio (o/e) 0.62, 90% interval 0.49 to 0.79. Synonymous variants: 20 observed, 41.88 expected, observed/expected ratio (o/e) 0.48, 90% interval 0.34 to 0.69.
Homologues: Orthologues: mouse Nrg1 (92% identical).